CD274 (CD274 molecule)
Diseases named in the same sentence as CD274 in open-access papers (continued):
Sharing a sentence is not in itself a finding about the gene and the disease.
cancer (continued). "Cancer cells evade T-cell recognition and autoimmune rejection by expressing the immune checkpoint molecule programmed death 1 ligand 1 (PD-L1/CD274), the ligand of the T-cell inhibitory receptor programmed death 1 (PD-1/CD273) ligand." (PMID 34447354, 2021). "Evidence indicates that NKX2‐1‐AS1, a lncRNA, suppresses the migration of human carcinoma cells by negatively regulating CD274/PD‐L1 and cell‐cell interaction genes." (PMID 33512745, 2021). "Due to the importance of PD-L1 pathway in cancer development, PD-L1 (also known as CD274 or B7-H1) expression is one of the earliest and most promising predictive biomarkers." (PMID 32612833, 2020). "The ligand for PD1 is programmed cell death 1 ligand 1 (PDL1/CD274) that is also overexpressed in various cancers." (PMID 32766150, 2020). "The inhibition of immune checkpoints such as programmed cell death ligand-1 (PD-L1/CD274) with antibodies is providing novel opportunities to expose cancer cells to the immune system." (PMID 33718115, 2020). "Cancer cells respond to interferon by production of a PD-1 ligand, transmembrane protein (PD-L1, CD274/B7-H1)." (PMID 32937961, 2020). "This suggests that IRE1α is an important, IFNγ-independent regulator of CD274 in macrophages in cancer." (PMID 32520957, 2020). "The IFN-γ-mediated PD-L1 upregulation occurs mainly through JAK/STAT/IRF1 signaling pathway activation in several types of cancers, including NSCLC, resulting in binding of IRF1 to the CD274 promoter." (PMID 33114576, 2020). "There results validated that CD47 and CD274 were highly expressed in a series of mouse cancer cells." (PMID 30872703, 2019). "Programmed death-ligand 1 (PD-L1) is a type 1 transmembrane protein that is encoded by the CD274 gene in humans and is overexpressed in some kinds of cancers." (PMID 31835799, 2019). "Samples showing positive PD-L1 protein expression, in either stromal or cancer cells, had significantly higher PD-L1 (CD274) mRNA expressions than samples showing no PD-L1 protein expression." (PMID 30967156, 2019). "Our data demonstrated that the synergy anti-CD47 and anti-CD274 showed the least number of tumorigenesis, and the inhibition cancer metastasis effect was more obvious than antibody alone." (PMID 30872703, 2019). "Cancer cells of different histology can express programmed death-ligand 1 (PD-L1, CD274, B7-H1), either constitutively or in response to immune-derived signals such as interferon (IFN)." (PMID 31234464, 2019). "Ligands for PD1 (CD274 encoding PD-L1 and PDCD1LG2 encoding PD-L2) were minimally expressed in cancer cells." (PMID 31427603, 2019). "B7-H1 (CD274), a T-cell coinhibitory molecule, often expressed in human carcinoma cells, believed to be implicated in the immune escape process also appears to favor EMT." (PMID 31934531, 2019). "Accordingly, epithelial cells have been shown to express high major histocompatibility (MHC) class I and low CD274 (PD-L1) levels, while more mesenchymal carcinoma cell lines exhibiting EMT markers expressed low levels of MHC-I, high levels of PD-L1." (PMID 31623163, 2019). "Its ligand, programmed death receptor 1 ligand 1 (PD-L1, CD274, B7-H1), is expressed on cancer cells and immune cells and plays a crucial role in blocking the “cancer immunity cycle”." (PMID 29568405, 2018). "Up-regulation of CD274 in immune cells and several cancer cells was reported to be mostly dependent on TLR or IFN-γ." (PMID 30341238, 2018). "We analyzed clinical data of 510 HNSCC patients in the cancer genomic atlas (TCGA) database and investigated how CD274 (gene type of PD‐L1) expression was related to patient prognosis." (PMID 29761938, 2018). "CD274 was detectable in epithelial cells from normal colonic mucosa, and, importantly, in cancer cells." (PMID 30353144, 2018). "Programmed death ligand 1 (PD-L1; also called B7-H1 or CD274) can be detected in many cancer cells and immune cells including the antigen-presenting cells (APCs)." (PMID 29789013, 2018).
cancer (continued). "The programmed death ligand 1 (PD-L1 or CD274) plays a major role in preventing the immune response in many cancer types." (PMID 28178682, 2017). "Our data provide a potential explanation for the genomic structural variations in the CD274 3′ UTR observed in human cancer." (PMID 29246442, 2017). "In line with this prediction, primary cancer cells also expressed CD274, which was further enhanced by inducing a more invasive phenotype using macrophage-conditioned medium." (PMID 28423491, 2017). "Recently, innate and adaptive immune resistance induced by CD274 has been reported in many types of cancers." (PMID 27855694, 2016). "7/13 carcinomas with strong, membranous PD-L1 immunostaining (score 3+) showed high or low level CD274/PD-L1 amplification, 3/13 showed a polysomy and 3 cases displayed a normal copy number status." (PMID 26918453, 2016). "In line with their immunosuppressive phenotype, several molecules, known to be linked to cancer progression and immune evasion, were highly expressed (>80%: CD47, CD274, CD276, and Indoleamine 2,3 dioxygenase-1)." (PMID 26618628, 2015). "EBV positive carcinomas show recurrent PIK3CA mutations, extreme DNA hypermethylation, and amplification of JAK2, CD274, and PDCD1LG2." (PMID 25859432, 2015). "Consequently, the therapeutic blockade of CD279/CD274 axis has become a cornerstone of modern cancer immunotherapy." (PMID 41409271, 2025). "Strikingly, ACACA expression exhibited significant negative correlations with the immune checkpoint-related genes (PDCD1, LAG3, LAGLS9, IDO1, CD244, CTLA4 and TIGIT), while showing positive associations with other genes (TGFBR1, KDR, IL10RB, CD160 and CD274) across most cancer types." (PMID 41169354, 2025). "Besides, we also found that only CD276 was positively associated with UBA1 in most cancers, however, there are many other immune checkpoints like CD44, CD86 and CD274 illustrating a positive correlation with UBA6." (PMID 40046044, 2025). "Thus, similar to PDCD and CD274, the altered expression of some of the cytokines in the blood likely also contributes to the anti-aging and/or anti-cancer characteristics of the Klf1(K74R) mice." (PMID 38752723, 2024). "Targeted/global gene expression profiling analysis has identified changes in the expression of specific proteins, including the immune checkpoint factors PDCD and CD274, and cellular pathways in the leukocytes of the Klf1(K74R) that are in the directions of anti-cancer and/or anti-aging." (PMID 38752723, 2024). "Notably, we observed a significant association between PRNP(PrPC) and the majority of immune checkpoint molecules across various cancer types, particularly robust correlations with CD274 and C10orf54." (PMID 39170916, 2024). "Our results showed that NAMPT and PD-L1 (CD274) are highly expressed in most cancers." (PMID 38448544, 2024). "We found that prioritized ligands with a high impact on cancer gene expression, including Fn1, Mmp9, and Cd274, were mainly expressed in myeloid cells, suggesting that the molecular changes of cancer cells may be induced by myeloid cells." (PMID 38169569, 2024). "Ccr7+Ido1+ DCs within the immunity hubs identified in our current study not only showed expression similarity with CCR7+LAMP3+IDO1+CD274+ activated DCs or mregDCs identified in human cancers, but also showed similar spatial co-localization with CD4+ and CD8+ T cells." (PMID 39414763, 2024). "Reculstering of IFNγ pathway genes showed a shifted expression profile in the IFNγ pathway in sh61A CAL 27 cells, with pronounced downregulation of CD274 and CD47, reinforcing the conclusion that TRMT61A is critical to the reactive upregulation of PD-L1 on cancer cells during inflammation." (PMID 38730256, 2024). "Additionally, genes such as CD274 (PD-L1), associated with immune checkpoints, exhibit high expression in NRF2-activated cancer cells." (PMID 38241355, 2024).
cancer (continued). "Interactions of several ligand-receptor pairs between cancer cells and immune cells (CD274:PDCD1, FAM3C:PDCD1, PVR:TIGIT) are predicted to be enhanced in NRF2 signature high samples which could be potential targets to inhibit to remodel the TME." (PMID 38241355, 2024). "Also recognized as CD274, PD-L1 contributes to inhibiting the cancer immunity cycle by binding to negative regulators of T-cell activation, such as PD-1 and CD80." (PMID 39335671, 2024). "Of note, the in vivo levels of Pdcd1 (encoding PD-1) or Cd274 (encoding the PD-1 ligand PD-L1), both in vivo and in cultured cancer cells, were not altered by CDA depletion." (PMID 38844817, 2024). "Drugs targeting MST1, ITPKA, CD274 were mainly designed to treat cancers." (PMID 36857861, 2023). "The question is, how is CD274 upregulation, especially in cancer cells, achieved?" (PMID 37190121, 2023). "We observed that the immune checkpoint inhibitor, PD-L1 (CD274), a ligand for T cell surface receptor PD-1, was expressed on the cancer cell surface of PW(+) and MA groups similar to the PW(−) group, compared to isotype control (p < 0.001, p < 0.01, or p < 0.01, respectively)." (PMID 37762490, 2023). "In addition, nine out of ten miR candidates best describing CXCR4 overexpression within the pan-cancer cohort were reported to regulate immune-related target genes such as PD-L1 (CD274)—thereby confirming ML results based on mRNA expression." (PMID 36672341, 2023). "CD274 (PD-L1) is considered a major prognostic biomarker for immunotherapy of many cancers." (PMID 37351101, 2023). "CD274/PD-L1 molecules are overexpressed in several types of cancer." (PMID 37675121, 2023). "Besides proimmune factors, combination treatment led to a significant increase of Cd274 in both M1 and M2, suggesting a self-limiting mechanism of immune regulation and an important role of macrophage-expressed PD-L1 in cancer immunotherapy." (PMID 37546701, 2023). "Therefore, the application of anti-CTLA4, anti-PDCD1 (PD-1) and anti-CD274 (PD-L1) agents is becoming a promising therapeutic option in several types of cancers." (PMID 36845098, 2023). "The introduction of immunotherapy into clinical practice represents a significant development in cancer treatment, with the PD-1/PD-L1 (programmed death ligand 1; CD274; gene CD274) pathway being a primary target of this strategy in several cancers, including NSCLC." (PMID 36759392, 2023). "The EBV-positive subgroup showed distinctive molecular characteristics, including, but not limited to, the highest hypermethylation rates in the host DNA compared to other cancers, frequent mutations in the PIK3CA, JAK2, and CD274 (PD-L1) genes, and deletions in key tumor suppressor genes." (PMID 37511034, 2023). "Immune checkpoint inhibitors, such as those targeting cytotoxic T lymphocyte‐associated molecule 4 (CTLA‐4), programmed cell death receptor 1 (PDCD1, also named PD‐1), and programmed cell death ligand 1 (CD274, also named PD‐L1), have revolutionized cancer treatment." (PMID 37904707, 2023). "The receptor protein PD-1 (CD279) and its ligand PD-L1 (CD274) have attracted much attention due to the discovery of clinically useful anti-cancer antibodies or drugs such as pembrolizumab that inhibit their interaction or bind to one or the other of the two proteins." (PMID 37296860, 2023). "Notably, in the PD-1/PD-L1 cancer immunotherapy pathway, CD274, the gene that transcribes PD-L1, PDCD1LG2, the gene that transcribes PD-L2, and PTPN11, the gene that encodes SHP2 are all predicted to be activated by IFNγ in astrocytes." (PMID 37828609, 2023). "Interestingly, the contribution of IRF1 to CD274 expression relative to that of other significant TFs differed amongst cancer types (15% [SD: 1.4] in BRCA, 26% [SD: 2.1] in LUAD, and 56% [SD: 3.9] in SKCM)." (PMID 35289334, 2022).
cancer (continued). "Moreover, negative regulatory genes of cancer-immunity cycle (CIC) illustrated that immunosuppressors TGFB1, VEGFA, and CD274 (PDL1) were all positively correlated with risk-scores." (PMID 35222383, 2022). "Finally, by considering the genes recapitulating IL-3 biological functions, we proposed a model, including IL-3Rα, SNAI1, ZEB1, VIM, CTNNB1, MMP2, SPRY2, and CD274, that remarkably discriminates cancer aggressiveness (AUC = 0.86 95% CI = 0.82–0.89)." (PMID 36010912, 2022). "Immuno-independent effects of CD274 have been reported for cancer cells." (PMID 36009475, 2022). "We systematically analyzed TMB, MSI, and the expression of CD274 across cancers." (PMID 36091049, 2022). "In addition, combination therapy with CD274 inhibitors and Bifidobacteria can nearly completely inhibit the growth and development of cancer cells." (PMID 35463305, 2022). "The ability of HPV integration to alter expression of nearby human genes (within 500 Kb) has been demonstrated in both OPSCC and UCSCC with recurrent integration sites identified near genes implicated in cancer such as MYC, MYB, PVT1, RAD51B, EMBP1, CD274/PD-L1, and SOX2." (PMID 36139648, 2022). "For these cancers, overall CD274 expression was much lower than in BRCA, LUAD and SKCM patients." (PMID 35289334, 2022). "Moreover, diagnostic values of CD274 and PDCD1LG2 in various cancers were confirmed using ROC curves." (PMID 36276934, 2022). "Programmed death-ligand 1 (PD-L1), also known as CD274, is a transmembrane protein that binds to the inhibitory receptor PD-1 on T cells and elicits T cell anergy, leading to immune suppression, Many cancer cells upregulate PD-L1 surface expression to escape immune surveillance." (PMID 36316684, 2022). "Together, they indicate that the breast APC population, which is competent to generate CAFs, may also be an important source of CD274 and contribute significantly to cancer immune escape." (PMID 36009475, 2022). "In conclusion, a generalized model developed by using combined data of common cancers demonstrated superior MLR extrapolation capacity and can thus be used to predict CD274 expression in other cancer types and to identify patients in whom expression is high relative to the observed TF activity." (PMID 35289334, 2022). "Furthermore, TOP2A was positively associated with expression of immune checkpoints (CD274, CTLA4, HAVCR2, LAG3, PDCD1 and TIGIT) in most cancer types." (PMID 35778520, 2022). "Although this discussion on dominance of TFs highlights that our approach correctly identified differential CD274 regulation between cancer types, our generalized model based on an ensemble of patients with different cancer types was also good at predicting CD274 expression." (PMID 35289334, 2022). "Cancer cells often overexpress the immune checkpoint protein PD-L1 (CD274)." (PMID 35011741, 2022). "Furthermore, CCNA2 is positively associated with expressions of immune checkpoints (CD274, CTLA4, HAVCR2, LAG3, PDCD1, and TIGIT) in most cancer types." (PMID 35480884, 2022). "Our results revealed that in GBM cancer cells, expression of CD274 (PD-L1), PDCD1LG2 (PD-L2), LGALS9 (Galectin-9), and PVR (CD155) were positively correlated with the expression of multiple m6A regulators, especially YTHDF2, YTHDF3, LRPPRC, METTL3, RBM15B, FTO, and ALKBH5." (PMID 35558067, 2022). "We finally analyzed transcriptome profiles of ICI-treated patients and associated their response with high levels of IFNγ, Merck18, CD274, CD8, and low levels of myeloid-derived suppressor cells (MDSCs), cancer-associated fibroblasts (CAFs) and M2 macrophages, irrespective of their TMB status." (PMID 36389735, 2022). "Since ILK correlation with the immune inhibitory molecules was greater in COAD, we decided to further investigate whether ILK is implicated in regulating PD-L1 (CD274) protein expression in CRC cell lines in vitro, our focused cancer model in this study." (PMID 35692780, 2022).
cancer (continued). "We observed that P+G+ samples were associated with significantly worse patient survival when compared to the P+G− across multiple cancers, indicating that a concurrent upregulation of CD274 expression and glycolysis signatures results in more aggressive disease progression in a pan-cancer manner." (PMID 36354714, 2022). "We systematically evaluated TMB, MSI as well as the expression of CD274 among pan-cancer." (PMID 36527013, 2022). "However, the association of CD36 expression with CD274 (PDL-1) and CTLA4 was inconsistent among different cancer types." (PMID 34234847, 2021). "Furthermore, in several human cancer cells, IL-27 increased CD274 transcription by promoting the tyrosine phosphorylation of STAT1 and STAT3." (PMID 33413496, 2021). "PDCD1 (PD-1, CD279) and CD274 (PD-L1) axis has been discovered as a worthy therapeutic target for its important role not only in physiological immune homoeostasis, but also in the way through which cancer cells evade the immune system." (PMID 33648519, 2021). "As a result, in all seven cancer types, CD274/PDCD1LG2 was correlated with at least one DNMT gene." (PMID 33833994, 2021). "The CD274/PDCD1LG2 expression among the different cancer cell lines was reported." (PMID 33833994, 2021). "Although 49 microRNAs were identified as linked to the CD274/PDCD1 network and many showed survival relationships (with 130 significant survival relationships being identified across fourteen cancer types), it is beyond the scope of this article to validate each of them." (PMID 34067485, 2021). "However, the association of CD36 expression with CD274 (PDL-1), TIGIT, and TNFRSF25 was cancer type-specific." (PMID 34234847, 2021). "PDL1, encoded by CD274, is an immune checkpoint protein upregulated on cancer cells." (PMID 34638403, 2021). "To explore whether PD-L1 could exert the similar effect in BC cells, we transfected 5637 and T24 cancer cells with lentivirus carrying CD274 transcript sequence." (PMID 34512159, 2021). "Notably, the present work also demonstrated that the expression of CD274/PDCD1LG2 was related to cancer immunity." (PMID 33833994, 2021). "Knocking down or inhibiting Myc in cancer cells reduced CD274 mRNA and PD-L1 protein." (PMID 33413496, 2021). "Besides, the expression of HLA family genes and CD274 gene of cancer tissue sample in three groups was analyzed." (PMID 34306024, 2021). "We further explored the correlation between YTHDC2 and eight immune checkpoint‐related genes and found that YTHDC2 was significantly associated with the expression of SIGLEC15, IDO1, CD274, HAVCR2, PDCD1, CTLA4, LAG3 or PDCD1LG2 in almost all types of cancers except for CESC and TGCT." (PMID 34312987, 2021). "Cancer cells and immune cells may interact via programmed cell death ligand-1 (PD-L1/B7-H1/CD274) and its receptor programmed cell death-protein 1 (PD-1)." (PMID 34572318, 2021). "The HS group has a higher expression level of CD274 (p < 0.0001), suggesting cancer patients with a high ferroptosis score may be more likely to benefit from PD-L1 inhibitors." (PMID 34938739, 2021). "In all seven cancer types, CD274/PDCD1LG2 was correlated with at least one MMR gene." (PMID 33833994, 2021). "Moreover, CTLA4, PDCD1 (PD-1), and CD274 (PD-L1), as the primary immune checkpoints in cancers, had the highest expression level in IS2 and the lowest level in IS1 (p < 0.05)." (PMID 34404444, 2021). "Moreover, CD36 expression presented a disease-specific association with CD274 (PDL-1) and CTLA4 among different cancer types." (PMID 34234847, 2021). "Furthermore, we analyzed the correlation of the mRNA levels between GNG12 and PD‐L1 (also known as CD274) using The Cancer Genome Atlas datasets and GEPIA web tool." (PMID 31898405, 2020). "PD-L1/CD274 expression of monocytes and blood DC could be involved in cancer-induced immune suppression and can be used as a blood biomarker for poor response to PD1 inhibitor therapy." (PMID 33066260, 2020).